DNMT1 (DNA methyltransferase 1)
Diseases named in the same sentence as DNMT1 in open-access papers (continued):
Sharing a sentence is not in itself a finding about the gene and the disease.
breast cancer (continued). "In summary, these findings suggest that DNMT1 promotes breast cancer cell proliferation, migration, and invasion by methylating and silencing RASSF1A." (PMID 41381440, 2025). "DNMT1 exhibited elevated expression in CSCs and was significantly upregulated in brain metastasis samples compared to in situ breast cancer samples." (PMID 41381440, 2025). "This DIVA method opens a new perspective for using plasma DNMT1 as a monitoring indicator in the clinical tumor burden assessment and neoadjuvant therapy response prediction of breast cancer." (PMID 40317882, 2025). "Another 121 clinical samples were recruited and revealed significant differences in plasma DNMT1 activity among patients with different stages of breast cancer." (PMID 40317882, 2025). "DIVA can detect plasma DNMT1 at levels as low as 10−7 U mL−1, also it successfully evaluated tumor burden and predicted the neoadjuvant therapy responses of breast cancer patients." (PMID 40317882, 2025). "Here, a reaction system is developed known as DNMT1 Identification by Variable Activity (DIVA) for the highly sensitive detection of DNMT1 activity in the peripheral blood of breast cancer patients." (PMID 40317882, 2025). "In summary, the outcomes indicate that DNMT1 can promote the proliferation, colony formation, migration, and invasion abilities of breast cancer cells." (PMID 41381440, 2025). "Our findings demonstrate that DNMT1 promotes breast cancer brain metastasis by regulating RASSF1A DNA methylation, providing a novel strategic direction for therapeutic intervention." (PMID 41381440, 2025). "While these in silico findings support the affinity of hinokitiol for DNMT1, further experimental validation is necessary to confirm its biological mechanism of action in breast cancer therapy." (PMID 40661180, 2025). "DNMT1 is identified as a crucial element in preserving the stem characteristics of leukemia cells and breast cancer cells." (PMID 40050970, 2025). "In summary, our study demonstrates that DNMT1-driven RASSF1A DNA methylation in CTCs plays a pivotal role in early brain metastasis of breast cancer." (PMID 41381440, 2025). "In the context of breast cancer, the circular RNA circ-Dnmt1 is significantly upregulated in multiple breast cancer cell lines and patients diagnosed with breast carcinoma, and silenced circ-Dnmt1 decreases cell proliferation and survival rates." (PMID 39996888, 2025). "For example, in breast cancer, elevated expression of DNMT1 is observed in M2 macrophages via the IL-6-pSTAT3-ZEB1-DNMT1 axis." (PMID 40380196, 2025). "Overall, these findings suggest that RASSF1A is a key methylation-regulated gene potentially silenced by DNMT1, contributing to the metastatic progression of breast cancer to the brain." (PMID 41381440, 2025). "Due to the upstream role of epigenetic alterations in breast cancer phenotypes, we attempted to establish a method for tumor burden assessment by monitoring the DNMT1 activity levels in plasma samples from patients with different stages of breast cancer." (PMID 40317882, 2025). "Taken together, the results suggest that DNMT1 downregulation suppresses brain metastasis of breast cancer by reducing RASSF1A promoter methylation and restoring its expression, thereby impairing the metastatic potential of breast cancer cells." (PMID 41381440, 2025). "Our subsequent functional and methylation-based mechanistic experiments confirmed that DNMT1 promotes breast cancer brain metastasis through the regulation of RASSF1A methylation, thereby complementing the limitations of the database analysis." (PMID 41381440, 2025). "In summary, our findings identify DNMT1 as a key epigenetic regulator that facilitates breast cancer brain metastasis by repressing RASSF1A and modulating downstream signaling pathways." (PMID 41381440, 2025).
breast cancer (continued). "In our study, we demonstrated that DNMT1 overexpression played a critical role in the development and progression of breast cancer brain metastases, primarily through the epigenetic silencing of RASSF1A via DNA methylation." (PMID 41381440, 2025). "For instance, circ-DNMT1 enhances the nuclear localization of AUF1, thereby reducing the degradation of DNMT1 mRNA and promoting its translation, which contributes to breast cancer progression." (PMID 41194937, 2025). "Most notably, CDK4 and DNMT1 are inhibited by FDA-approved drugs for the treatment of luminal breast cancers and bone marrow diseases, respectively, despite being common essential genes." (PMID 40378956, 2025). "DNA methyltransferases, such as DNMT1, DNMT3A, and DNMT3B, have been implicated in the progression of multiple malignancies including breast cancer and acute myeloid leukemia." (PMID 40427627, 2025). "In glioblastoma and breast cancer, DNMT1 controls the methylation of the miRNA-20a promoter, thereby regulating the proliferation, invasion, and apoptosis of tumor cells." (PMID 39996888, 2025). "For example, According to one study, DNMT1-mediated FOXO3a promoter hypermethylation reduces FOXO3a expression in breast cancer, and FOXO3a decreases breast cancer stem cell characteristics and tumorigenicity through lowering FOXM1/SOX2 signaling." (PMID 38436027, 2024). "DNMT1 has been identified as a target gene of miR-148a in human bone mesenchymal stromal cells and breast cancer." (PMID 39201245, 2024). "This study investigates the impact of genetic polymorphisms in DNA methyltransferases (DNMT1 and DNMT3A) on breast cancer pathomorphology and patient prognosis." (PMID 39597087, 2024). "MiR-148a regulates the expression of the estrogen receptor through DNMT1-mediated DNA methylation in breast cancer cells." (PMID 38890707, 2024). "In the present study, 30 μM of TQ significantly decreased mRNA expression levels of the DNMT1 gene in breast cancer cell lines." (PMID 38257347, 2024). "DNMT1 gene deletion confers resistance to DNMTi in colorectal, breast cancer, and ovarian cancer cells using the gene knockout approach." (PMID 39057134, 2024). "Further research is needed into the mechanisms by which TQ regulates the expression of DNMT1 in breast cancer cells and the related events." (PMID 38257347, 2024). "In conclusion, we propose that TQ is a promising drug for breast cancer through its ability to target DNMT1." (PMID 38257347, 2024). "Research has demonstrated that HDACis can downregulate the expression of the DNMT1 protein within the nucleus in human breast cancer cells, while inhibiting HDAC3 can increase the acetylation level of DNMT1, thereby decreasing its stability." (PMID 38490978, 2024). "In summary, we demonstrate the existence of PAX5-miR-142-5p/3p-DNMT1/ZEB1 feedback loop in regulation of breast cancer." (PMID 37403081, 2023). "For example, piR-651 promoted cell proliferation and migration in breast cancer by suppressing Pten via recruiting DNA methyltransferase 1 (DNMT1) to its promoter region." (PMID 37153732, 2023). "Examples within breast cancer include DNMT-1 gene disinhibition and SIRT4 loss, mediated by hypermethylation, which promotes breast cancer self-renewal." (PMID 36900364, 2023). "Our goal was to identify TOP2A- or DNMT1-enriched TECs that resembled our findings in the mouse mammary tumor models." (PMID 37055433, 2023). "While miR-142-5p was found to inhibit the cell invasion and migration by targeting DNMT1 in breast cancer." (PMID 37403081, 2023).
breast cancer (continued). "Correlation of the function of certain genes with underlying cellular metabolites was interpreted by observing cell survival and migration pattern of MDA-MB-231 breast cancer cells after knockdown of DNMT1 and specific inhibition of HDAC1 & HDAC2." (PMID 36774386, 2023). "It was demonstrated in the human breast cancer MCF-7 cell line that curcumin was able to inhibit DNMT1 activity." (PMID 36982583, 2023). "Locally advanced breast cancer patients with high levels of DNMT1 in breast stromal fibroblasts have poor survival, because DNMT1 promotes angiogenesis through IL-8/VEGF-A upregulation." (PMID 37496657, 2023). "In this study, we demonstrate that DNMT1 is overexpressed in breast cancer and that DNMT1 promotes breast cancer tumorigenesis and metastasis." (PMID 36273188, 2022). "It has been found that DNMT1 expression is overexpressed in breast cancer, and mammary gland-specific DNMT1 deletion protects in vivo mouse model from breast cancer tumorigenesis by reducing BCSC pool." (PMID 39086963, 2022). "To explore the relationship between DNMT1 and PAS1 expression, we firstly examined the PAS1 RNA level by RNA in situ hybridization and DNMT1 protein levels by immunohistochemical staining of human breast cancer tissue arrays." (PMID 35307730, 2022). "In lieu of these findings, DNMT1 was believed to promote chemotherapy resistance and metastasis of breast cancer cells." (PMID 35255904, 2022). "Another study pointed out that exosomal H19 promotes proliferation and invasion of breast cancer using miR-152/DNMT1 axis, providing a new mechanism for breast cancer development." (PMID 36203417, 2022). "We have clearly demonstrated that DNMT1 is required for breast cancer cell proliferation and migration in vitro and in vivo." (PMID 36273188, 2022). "Altogether, DNMT1 inhibits miR-497 and elevates GPRC5A expression through methylation to promote chemotherapy resistance and metastasis in breast cancer, which sheds a new light on the anti-tumor significance of DNMT1 in regard to breast cancer." (PMID 35255904, 2022). "Taken together, our above in vivo data indicate that DNMT1 plays a pivotal role in breast cancer tumorigenesis and distant metastasis." (PMID 36273188, 2022). "Overall, our data show that DNMT1 is necessary for TAM-induced breast cancer cell migration in the TME." (PMID 36273188, 2022). "Lastly, our findings revealed that down-regulation of DNMT1 inhibited growth and metastasis of breast cancer cells in nude mice." (PMID 35255904, 2022). "Knockdown of DNMT1 inhibited progression of breast cancer cells by enhance MEG3 expression through demethylation." (PMID 35109842, 2022). "One such tumor suppressor gene (TSG) RUNX3 (Runt-related transcription factor 3) has been a new insight in breast cancer known to be suppressed due to local promoter hypermethylation mediated by DNA methyltransferase 1 (DNMT1)." (PMID 35898303, 2022). "TAMs promote DNMT1 expression in breast cancer cells via the IL-6-pSTAT3-ZEB1-DNMT1 axis in the TME." (PMID 36273188, 2022). "The IHC data revealed that the ZEB1 and DNMT1 expression levels were much higher in breast cancer tissues with high CD163 expression." (PMID 36273188, 2022). "In this study, we demonstrate that DNMT1 can promote breast cancer cell proliferation and tumorigenesis in vitro and in vivo." (PMID 36273188, 2022). "It was showed that DNMT1 protein expression was significantly high in breast cancer cells, while MEG3 was significantly lowly expressed (p < 0.05)." (PMID 35109842, 2022). "So far, the individual role of RUNX3 as a TSG in breast cancer and DNMT1 as the methylation maintenance protein has been reported in various scientific studies." (PMID 35898303, 2022). "Subsequently, we found that ectopic expression of DNMT1 promotes MCF7 breast cancer cell proliferation, while knockdown of DNMT1 inhibits MCF7 breast cancer cell proliferation." (PMID 36273188, 2022).
breast cancer (continued). "In contrast, we also discovered that knockdown of DNMT1 strongly suppressed breast cancer cell migratory and invasive behaviours in invasive MDA-MB-231 cells." (PMID 36273188, 2022). "We applied immunohistochemistry to evaluate the level of DNMT1 in breast cancer tissues and their adjacent normal counterparts." (PMID 35719957, 2022). "And we also want to explore the role of DNMT1 in tumour microenvironment promoting breast cancer progression." (PMID 36273188, 2022). "Subcutaneous xenograft tumor model in nude mice was established to detect effects of DNMT1 on growth and metastasis of breast cancer in vivo." (PMID 35255904, 2022). "Consistent with DNMT1 playing a general role in the regulation of cell differentiation, overexpression of DNMT1 in breast cancer, pituitary adenomas, and B-cell lymphoma resulted in alteration of both CG methylation and gene expression." (PMID 35246225, 2022). "In the same way, circFECR1 also downregulates DNMT1, an enzyme that is responsible for sustaining DNA demethylation during DNA replication, thereby regulating TET1 and DNMT1, and their subsequent effects are observed in breast cancer (BC) progression." (PMID 35223470, 2022). "It is reported that DNMT1 can promote the malignant progression of breast cancer, while MEG3 can elicit a suppressive effect." (PMID 35109842, 2022). "In this study, we demonstrate that DNMT1 is highly expressed and promotes breast cancer cell proliferation and migration in vitro and in vivo." (PMID 36273188, 2022). "We verified their mRNA level in breast cancer cell lines by RT-qPCR, and found that DNMT1 knockdown led to an obvious upregulation of PAS1." (PMID 35307730, 2022). "In HCC1806 breast cancer cells, resveratrol downregulates the DNMT1, DNMT3a, DNMT3b, and negatively regulated hTERT with the inhibition of SIRT followed by the inhibition of breast cancer cell growth." (PMID 36235389, 2022). "This means that DNMT1 is highly expressed both in breast cancer cell lines and in breast cancer tissues." (PMID 36273188, 2022). "Altogether, these findings indicated that DNMT1 inhibited the expression of miR-497 through methylation modification, thereby promoting breast cancer chemotherapy resistance and metastasis." (PMID 35255904, 2022). "For example, the high expression of DNA methyltransferase 1 (DNMT1) in breast cancer cell influenced of methylation in the PTEN promoter thus leading to the loss of PTEN." (PMID 35705830, 2022). "DNMT1 performs oncogenic functions in breast cancer by inhibiting ER expression, inducing EMT, promoting cell autophagy, and increasing CSCs." (PMID 35743249, 2022). "We discovered that ZEB1 activates DNMT1 expression in breast cancer cells by recruiting P300 binding to the DNMT1 promoter and increasing its acetylation." (PMID 36273188, 2022). "Our results also demonstrated that DNMT1 was expressed at high levels in breast cancer patients with high ZEB1 expression." (PMID 36273188, 2022). "It has been reported that DNMT1 interacts with PARP1 to regulate the sensitivity of breast cancer and acute myeloid leukemia cells to PARP inhibitors." (PMID 34854226, 2022). "The downregulation of DNMT1 has been reported to suppress progression of breast cancer cells, and DNMT1 also can downregulate maternally expressed gene 3 (MEG3) expression through increasing methylation level of MEG3 in breast cancer." (PMID 35109842, 2022). "The results showed that the DNA methyltransferase DNMT1 was dramatically overexpressed in breast cancer tissues compared with normal breast tissues." (PMID 36273188, 2022). "In conclusion, silencing DNMT1 inhibited the malignant progression of breast cancer via up-regulating MEG3." (PMID 35109842, 2022). "To further elucidate the regulatory effect of DNMT1 on breast cancer, we employed RT-qPCR and found that relative to MCF-10A cells, DNMT1 expression levels were strikingly increased in MCF-7/ADR and MCF-7 cells." (PMID 35255904, 2022).
breast cancer (continued). "Similar to the results above, self-renewal of liver cancer stem cells, breast cancer stem cells and leukaemia stem cells are regulated by DNMT1." (PMID 35838271, 2022). "High ZEB1 expression was also positively correlated with high DNMT1 expression in our detected TMA breast cancer tissues." (PMID 36273188, 2022). "Thereby, we investigated the link between the level of DNMT1 in breast cancer cells and their stromal fibroblasts with the survival of patients with LABC treated with neoadjuvant chemotherapy ± Trastuzumab." (PMID 35719957, 2022). "DNA hypermethylation participates in occurrence and cell survival of breast cancer, and its initiation mechanism is the abberrant expression of DNA methyltransferases (DNMTs), including DNMT1, DNMT3a and DNMT3b." (PMID 35109842, 2022). "DNMT1 is an epigenetic target for breast cancer cell damage and alters metastatic and aggressive phenotypes." (PMID 35743249, 2022). "Then, our western blot results also revealed that DNMT1 is highly expressed in various breast cancer cell lines (MDA-MB-231, MCF7, MDA-MB-453, etc.)compared with that in MCF10A cells (mammary epithelial cells)." (PMID 36273188, 2022). "Above all, we uncovered that DNMT1 promoted chemotherapy resistance and metastasis of breast cancer via inhibition of miR-497 expression through methylation modification." (PMID 35255904, 2022). "In breast cancer, all the isoforms of DNMT1, 3A, and 3B are overexpressed, and overexpression of DNMT3A was associated with poor prognosis in sporadic breast cancer." (PMID 34692471, 2021). "TCGA-based bioinformatic analysis revealed that expression levels of DNMT1, 3A and 3B altered in several cancers including breast cancers." (PMID 33604794, 2021). "Having the lowest ∆Gbinding and least-unwanted ADME-Tox properties, our results indicated that C-7756 has the potential to be a drug lead for inhibiting DNMT1 for breast cancer therapy." (PMID 33450856, 2021). "Our results demonstrated that DNMT1 plays a critical role in breast cancer development and PTX sensitivity." (PMID 34150611, 2021). "Ectopic circ-DNMT1 increases the proliferation and survival of breast cancer cells by triggering autophagy." (PMID 33718157, 2021). "Previous studies have shown that DNMT1 is an essential substance for the maintenance of cancer stem cells (CSCs) in various cancers such as prostate cancer, pancreatic cancer and breast cancer." (PMID 33616161, 2021). "Inhibition of DNMT1 enhanced the expression of the tumor suppressor genes Isl1 in mammary tumors and CSCs." (PMID 34051847, 2021). "Authors further showed that this destruction domain is dysfunctional in MCF-7 breast cancer cell lines compared to normal human breast epithelial cells and is responsible for differential expression of DNMT1 among these cell lines." (PMID 33604794, 2021). "DNMT3B transcripts were low compared to that of DNMT1 and 3A in different types of breast cancers and stages." (PMID 33604794, 2021). "For example, there is a negative regulatory circuit of miR-148a/miR-152 and DNMT1 in human breast cancer cells." (PMID 34062726, 2021). "DNMT1 inhibition or DNMT1 induced Islet-1 (ISL1) hypermethylation/down-regulation limits the number of CSCs in breast cancer cells." (PMID 33616161, 2021). "Another study showed that DNMT1 inhibition reduced tumor formation and metastasis in human and mouse breast cancer cells by lowering the CSC formation in them." (PMID 34051847, 2021). "Deacetylation at K1349 and K1415 residues of DNMT1 by SIRT1 has been shown to enhance the methyl transferase activity of enzyme in breast cancer cell lines." (PMID 33604794, 2021). "Our previous study showed that 6-TG induces FAS-mediated exogenous apoptosis and p21-dependent G2/M arrest in MCF-7 breast cancer cells by regulating DNMT1." (PMID 33470407, 2021). "The expression of Krüppel-like factor 4 (KLF4) and DNA-methyltransferase 1 (DNMT1) in breast cancer tissues were assessed by immunohistochemistry and Western blotting." (PMID 34150611, 2021).